CTSB (cathepsin B)
Diseases named in the same sentence as CTSB in open-access papers (continued):
Sharing a sentence is not in itself a finding about the gene and the disease.
COVID-19 (37 papers, 2020 to 2026). A disease caused by infection with severe acute respiratory syndrome coronavirus 2. "In particular, cathepsin B (CTSB) overexpression is associated with metastatic cancer, atherosclerotic plaques, neurodegenerative diseases, and other inflammatory diseases, including COVID-19." (PMID 35631388, 2022). "Mainly, in the different articles, the following types of proteases were analyzed, and it was observed that a high level of furin, cathepsin B, cathepsin L, and cathepsin G may increase the risk of COVID-19 complications." (PMID 35224542, 2022). "Moreover, CTSB is involved in the entry of the COVID-19 virus within cells via the endosomal pathway by cleaving and activating protein S. Additionally, expression of CTSB in COVID-19 may also lead to an increased risk of COVID-19 infection." (PMID 37037462, 2023). "It has also been proposed that patients with periodontitis show increased levels of different proteases (furin, cathepsin B, cathepsin L, cathepsin G), which may favour a more severe COVID-19, since they have been shown to increase the risk of complications in COVID-19 patients." (PMID 37133697, 2023). "Among the peptides/proteins enriched in the COVID-19-positive group were multiple members of the cathepsin family including cathepsin B, cathepsin D, and cathepsin S." (PMID 39861814, 2024). "Conversely, the activity of cathepsin D was lower in the urine of the COVID-19-positive participant group and the activity of cathepsin B was comparable between the two groups." (PMID 39861814, 2024). "The repurposing of known TMPRSS2 and CTSL/CTSB inhibitors can become an effective and safe treatment option for COVID-19." (PMID 37990007, 2023). "This module included the NUPR1 stress response gene as well as CSTB, which is an inhibitor of cathepsins like CTSL and CTSB that are involved in COVID-19 viral entry." (PMID 35007307, 2022). "CTSL and CTSL/CTSB increased in COVID-19 patients than in healthy individuals, and in severe patients than in nonsevere patients." (PMID 33774649, 2021). "The CTSL and CTSL/CTSB levels were markedly higher in patients with COVID-19 than in healthy volunteers, while the CTSB level was unchanged in the patients." (PMID 33774649, 2021). "Additionally, other inflammation-related molecules shared between OA and COVID-19, such as these encoded by HIF1A, CXCL10, and CTSB, contribute to the same pathophysiological bonfire." (PMID 38020136, 2023). "Indeed, most recent proteomic analysis of COVID-19 autopsies suggested an overall upregulation of the cathepsin family members, including CTSB, CTSD, CTSE, CTSH, CTSK, CTSS, and CTSZ, in the lung of the COVID-19 patients." (PMID 34335974, 2021). "Hence, the inhibition of cathepsin B has a positive effect on the alleviation of COVID-19." (PMID 37037462, 2023). "Additionally, cathepsin B may play a role in the hyperinflammatory response of COVID-19 and AAT inhibits neutrophil elastase induction of cathepsin B in vivo and in vitro." (PMID 37294003, 2023). "The results showed that significant targets of Vitex negundo compounds in COVID-19 are CSB, SERPINE1, and PLG which code for cathepsin B, plasminogen activator inhibitor-1, and plasminogen, respectively." (PMID 37037462, 2023). "Cardiac injury can be triggered by a number of direct and indirect mechanisms including viral injury and the interplay with host cells (COVID-19 spike protein (S), ACE2 receptor, host serine protease TMPRSS2, cathepsin B, and cathepsin L)." (PMID 37386548, 2022). "During the COVID-19 pandemic, it has been further demonstrated that SARS-CoV-2 can use CTSB and CTSL as well as TMPRSS2 for priming host cells." (PMID 34820418, 2021). "Despite the early findings relating ACE2 and TMPRSS2 to COVID-19, a link between SARS-CoV-2 infection outcome and other proteases such as furin and cathepsin B/L is yet to be established." (PMID 33036180, 2020).
COVID-19 (continued). "In our study, we evaluated plasma levels of ACE2, CTSL, and CTSB in COVID-19 patients with and without diabetes." (PMID 39150053, 2024). "Specially, the targets of the novel CPI such as AR, VDR, CTSL and Cathepsin B (CTSB) have been reported to be relevant for the treatment of COVID-19, thus these new predicted CPIs that have not been verified are good candidates for wet experiment exploration." (PMID 35275993, 2022). "We measured the plasma levels of COVID-19 related proteins, ACE2, CTSL, and CTSB in diabetic and non-diabetic COVID-19 patients." (PMID 39150053, 2024).
atherosclerosis (35 papers, 2012 to 2025). A disease characterized by the build-up of fatty material and calcium deposition in the arterial wall resulting in partial or complete occlusion of the arterial lumen. "CTSB is intimately associated with metabolic disorders such as type 2 diabetes, atherosclerosis, cardiac reperfusion injury, and chronic kidney disease through regulating the NLRP3 inflammasome in the cytoplasm." (PMID 39716081, 2024). "applied the cathepsin B‐sensitive NIRF probe (with the same structure as just described) in murine model to determine the potential of atherosclerosis associated activation of the cathepsin B‐sensitive probe using fluorescence‐mediated tomography (FMT)." (PMID 33344116, 2020). "CTSB’s role in cerebrovascular disease is similarly complex, particularly concerning atherosclerosis and cerebral aneurysms." (PMID 40407975, 2025). "CTSB is also involved in the development of several cardiovascular diseases, such as atherosclerosis, heart failure, myocardial infarction and so on." (PMID 40950552, 2025). "As indicators of autophagic activity, CTSB and cathepsin D are involved in the regulation of cell death and survival during the development of atherosclerosis." (PMID 37576397, 2023). "CTSB is involved in the pathophysiological processes of cardiovascular-related diseases, including atherosclerosis, myocardial infarction, hypertension, myocarditis, chemotherapy-induced myocardial injury, and heart failure." (PMID 37576397, 2023). "Cathepsin B is a lysosomal cysteine protease that plays an important role in cancer, atherosclerosis, and other inflammatory diseases." (PMID 35631388, 2022). "CTSS, CTSC, and CTSB are the main target molecules in the CTS family that are involved in atherosclerosis." (PMID 35186462, 2022). "Imbalances between cathepsin B and CysC were involved in atherosclerosis, glomerulosclerosis, and cardiomyopathy with senescence-associated phenotypes." (PMID 34456843, 2021). "The Cathepsins family, including cathepsin B and cathepsin D, potentially affects the entire processes involved in atherosclerosis." (PMID 33964876, 2021). "The ‘rs371316552’ SNP belongs to cathepsin B (CTSB), whose increased expression has been reported to pose a risk for atherosclerosis and myocardial infarction in rat models." (PMID 29420653, 2018). "Importantly, in cardiovascular diseases such as atherosclerosis, it was confirmed that CTSB is related to arterial stiffness and plaque instability, with serum levels reflecting the severity of peripheral arterial dysfunction." (PMID 41309848, 2025). "In atherosclerosis, CTSB contributes to arterial instability and stiffness by degrading the extracellular matrix within arterial walls, promoting macrophage apoptosis, increasing neuroinflammation, inducing pyroptosis in vascular smooth muscle cells, and promoting foam cell formation [1101–1104]." (PMID 40407975, 2025). "In our study, we utilized several machine learning algorithms to determine that LAPTM5, SLC40A1, TYROBP, CTSB, and PYCARD, which are related to macrophage genes, can act as diagnostic indicators for individuals with atherosclerosis and are linked to immune infiltration in this disease." (PMID 40881888, 2025). "Therefore, CTSB is a potential therapeutic target for atherosclerosis and is expected to provide new ideas and methods for the treatment of this disease." (PMID 40950552, 2025). "Importantly, recent data suggest that CTSB has significant impacts on different cardiac pathological conditions, such as atherosclerosis (AS), myocardial infarction, hypertension, heart failure and cardiomyopathy." (PMID 39248527, 2024).
atherosclerosis (continued). "In addition, cathepsin B (CTSB), a cysteine cathepsin associated with various diseases including rheumatoid arthritis, liver fibrosis and atherosclerosis, also has a pivotal role in the activation of NLRP3." (PMID 36551161, 2022). "In addition, CTSB was shown to strongly colocalize with macrophages, a finding which is consistent with those of earlier murine atherosclerosis studies; it also demonstrated that macrophage-derived CTSB plays an important role in atherosclerotic diseases." (PMID 35186462, 2022). "CTSB secreted by macrophages can post-translationally modify apoA-I by cleaving its C-terminal Ser228, thereby greatly reducing its lipid solubility, decreasing the ability of low-density lipoproteins to export cholesterol, and exacerbating the disease process of atherosclerosis." (PMID 37576397, 2023). "This study began with analyzing the GSE100927 and GSE23746 datasets to evaluate the expression levels of five key genes—TYROBP, CTSB, PYCARD, LAPTM5, and SLC15A3—in atherosclerosis-affected samples compared to normal controls." (PMID 40881888, 2025). "Our study highlights the important roles of LAPTM5, SLC40A1, TYROBP, CTSB, and PYCARD in the context of atherosclerosis." (PMID 40881888, 2025). "The results demonstrated significantly higher expression levels of LAPTM5, SLC40A1, TYROBP, CTSB, and PYCARD in the serum of atherosclerosis patients compared to the healthy controls." (PMID 40881888, 2025). "As an indicator of autophagic activity, CTSB and CTSD were involved in the regulation of cell death and survival in the development of atherosclerosis." (PMID 33964876, 2021). "Despite the opposite conclusion, to be sure, CTSB/CTSD played an important role in the development of SCD and involved the severity of atherosclerosis." (PMID 33964876, 2021). "The potential of cathepsin B, S, and K to influence ABCA1 protein level regulation further supports the concept for their implication in atherosclerosis." (PMID 28919859, 2017). "Besides CTSK, other members of the cathepsin family, including cathepsin B (CTSB) 52, cathepsin S (CTSS) 53, cathepsin L (CTSL) 54, and cathepsin C (CTSC) 55, also play a critical role in the development of atherosclerosis." (PMID 35673565, 2022). "The phagocytosis of oxLDL induces the expression of pro-IL-1β and ROS by the cathepsin B pathway, resulting in activation of the NLRP3 inflammasome, inducing macrophages to secrete IL-1β, and promoting macrophage transfer into foam cells during atherosclerosis." (PMID 36082127, 2022). "Based on the IogFc values, we observed that the differential expressions of CTSS, CTSB, and CTSC were the highest in atherosclerotic plaques and the expressions were positively expressed in advanced plaques, indicating a positive trend of promoting atherosclerosis." (PMID 35186462, 2022).
pancreatic cancer (35 papers, 1994 to 2026). "Researchers have identified high expression of CTSB in human pancreatic ductal adenocarcinomas and pancreatic cancer stem cells, and demonstrated its association with poor survival and surgical outcomes." (PMID 35872750, 2022). "In this pathway, cathepsin B was increased by 5 and 1.6 fold in patient and rat data, respectively, which is a key modulator triggering a cascade that causes pancreatic cancer." (PMID 33328982, 2020). "This inhibition also caused lysosomal permeabilization of pancreatic cancer cells leading to Cathepsin B release and a high cytosolic Cathepsin B activity." (PMID 22912777, 2012). "In non-neuronal systems, cathepsin-B expression is regulated by signal transducer and activator of transcription 3 (STAT3); the ferroptosis inducer erastin has been shown to cause lysosomal dysfunction and cathepsin-B upregulation via aberrant STAT3 activation in pancreatic cancer cells." (PMID 41304754, 2025). "Concomitant induction of pSTAT3 and cathepsin-B has also been reported in pancreatic cancer cells undergoing ferroptosis, consistent with our findings in neuronal HT22 cells." (PMID 41304754, 2025). "Cathepsin B has a strong potential to be used as biomarker for an early detection of pancreatic cancer." (PMID 40292193, 2024). "CTSB is expressed on the surface of pancreatic cancer stem-like cells and directly or indirectly affects the extracellular microenvironment." (PMID 37576397, 2023). "CTSB is also expressed in CSCs in head and neck cutaneous squamous carcinoma 144 and pancreatic cancer stem-like cells." (PMID 37576397, 2023). "The release of DNA from the nucleus to the cytosol caused by nuclear cathepsin B (CTSB)-mediated genomic DNA damage activates STING-dependent autophagy and leads to ferroptotic cell death in human pancreatic cancer cells." (PMID 34948027, 2021). "In a proteomic analysis, cathepsin D and its family member cathepsin B were identified as interacting partners of the anterior gradient 2 (AGR2) protein in pancreatic cancer cells and involved cell dissemination." (PMID 34439122, 2021). "Gem was also conjugated to the nanoparticles through a tetrapeptide linker that can be cleaved by lysosomal cysteine protease, cathepsin B, which is overexpressed in pancreatic cancer cells." (PMID 34522208, 2021). "It is well demonstrated that MMP-9 is overexpressed in the pancreatic tumor microenvironment while cathepsin B is up-regulated in the pancreatic tumor cells." (PMID 32850662, 2020). "For instance, the suppression of cathepsin B slowed down tumor progression by decreasing initiation, proliferation, angiogenesis, as well as invasion of pancreatic cancer." (PMID 33328982, 2020). "Cathepsin B is also a key player in the SPINK1 (serine protease inhibitor Kazal-type 1) pathway leading to pancreatic cancer." (PMID 33328982, 2020). "It induces the redistribution of lysosomal cathepsin B to the cytosol and activates downstream caspase-2 to induce mitochondrial depolarization and apoptosis in pancreatic cancer cells." (PMID 28402938, 2017). "The increased levels of CTSB/CTSD in cytosolic extracts confirmed the IMB-6G-induced LMP in pancreatic cancer cells." (PMID 28139733, 2017). "Hedgehog (Hh) signaling is involved in pancreatic cancer development and can regulate invasion by increasing cathepsin B expression." (PMID 28402938, 2017). "It was shown that in human pancreatic carcinoma cells bortezomib disrupted lysosomes with release of cathepsin B to the cytosol where it cleaved caspase-2 and induced mitochondrial apoptotic pathway." (PMID 25310712, 2014). "In the same study it was also seen that a Cathepsin B inhibitor was able to reverse the effects of HSP70 inhibition on the pancreatic cancer cells, indicating that lysosomal permeabilization is one of the earlier steps of apoptotic death in these cells." (PMID 22912777, 2012).
pancreatic cancer (continued). "Further, our results showed that MUC1-c protects pancreatic cancer cells from cell death by stabilizing lysosomes and preventing release of Cathepsin B in the cytosol." (PMID 22912777, 2012). "This indicated that release of Cathepsin B from the lysosomes of pancreatic cancer cells resulted in triggering the cell death pathways." (PMID 22912777, 2012). "Immunohistochemical analyses of pancreatic cancer tissues revealed that expressions of cathepsin B and cathepsin L are indicators of a poor prognosis." (PMID 22792318, 2012). "Enzymatic activity for cathepsin B was significantly downregulated for all 3 disease groups (localized, metastatic, and pancreatitis) compared to the healthy control group, which indicated that cathepsin B can successfully detect both pancreatic cancer and pancreatitis." (PMID 40292193, 2024). "Furthermore, the impact of cathepsin B on tumour formation and progression has been confirmed in multiple models, including the pancreatic cancer RIP1-Tag2 model and the renal cell carcinoma xenograft model." (PMID 37958596, 2023). "Dr Tang’s group recently discovered that DNA damage (mitochondrial DNA and nuclear DNA) induced by cathepsin B nuclear translocation or zalcitabine/erastin-induced mitochondrial stress activates cGAS-STING to trigger autophagy-dependent ferroptosis of pancreatic cancer cells." (PMID 35902564, 2022). "High expression levels of CTSB have been observed in various cancers such as breast, esophageal, gastric, colon, and pancreatic cancers, and hepatocellular carcinoma, and both advanced stage and poor survival in multiple cancers are known to be associated with greater expression of CTSB." (PMID 33333840, 2020). "Moreover, increased expression of UBL4A caused increased levels of LAMP1, LC3B, p62, and E-cadherin and resulted in decreased levels of CTSB, vimentin, and N-cadherin in the orthotopic pancreatic cancer models." (PMID 31288830, 2019). "Additionally, immunohistochemical results showed that the UBL4A level was positively correlated with the expression of LAMP1, LC3B, p62, and E-cadherin and negatively correlated with CTSB, vimentin, and N-cadherin in pancreatic cancer patients." (PMID 31288830, 2019). "Moreover, the vesicles staining for CTSB were observed more peripheral in the aggregated cells and the redistribution of CTSB vesicles toward the cell periphery may be induced by the acidic pericellular pH, which facilitates the progression and development of pancreatic cancer." (PMID 35872750, 2022). "In addition to mtDNA, the release of nDNA to cytosol caused by nuclear cathepsin B (CTSB)-mediated genomic DNA damage activates STING1-dependent autophagy and subsequent glutathione peroxidase 4 (GPX4) degradation, leading to ferroptotic cell death in human pancreatic cancer cells." (PMID 34078874, 2021). "Expression of L1CAM-CT induces transcription of pro-invasive proteins such as β3 integrin and cathepsin B, and downregulation of the tumor suppressor CRAPBPII, in ovarian and pancreatic cancer cells." (PMID 31455004, 2019). "While cathepsin B was able to significantly distinguish between localized and metastatic pancreatic cancer as well as localized pancreatic cancer and pancreatitis, it was not able to distinguish between metastatic pancreatic cancer and pancreatitis." (PMID 40292193, 2024). "In pancreatic cancer cells, AGR2 up-regulates the downstream effectors (e.g. cathepsin B and D) without changing their mRNA levels supporting that AGR2 could exert its effects on client proteins post-transcriptionally." (PMID 33717413, 2021).